HSD17B1P1 (hydroxysteroid 17-beta dehydrogenase 1 pseudogene 1)
Synonyms: SDR28C1P1; formerly EDHB17; EDH17B1; HSD17BP1
Gene: Transcribed unprocessed pseudogene on chromosome 17 (42,546,764 to 42,548,706, forward strand). Ensembl gene ENSG00000108785.
Diseases named in the same sentence as HSD17B1P1 in open-access papers:
HSD17B1P1 is named in the same sentence as 1 disease in open-access papers, as found by Europe PMC text mining. Sharing a sentence is not in itself a finding about the gene and the disease. The quoted sentences say what the papers report.
breast carcinoma (1 paper, 2020). "HSD17B1P1 is a pseudo-gene related to HSD17, which participates in steroid hormone biosynthesis, metabolism, and signaling pathways potentially related to breast cancer risk." (PMID 32115800, 2020).